TAF7 (TATA-box binding protein associated factor 7)
Description:
The TFIID basal transcription factor complex plays a major role in the initiation of RNA polymerase II (Pol II)-dependent transcription. TFIID recognizes and binds promoters with or without a TATA box via its subunit TBP, a TATA-box-binding protein, and promotes assembly of the pre-initiation complex (PIC). The TFIID complex consists of TBP and TBP-associated factors (TAFs), including TAF1, TAF2, TAF3, TAF4, TAF5, TAF6, TAF7, TAF8, TAF9, TAF10, TAF11, TAF12 and TAF13. TAF7 forms a promoter DNA binding subcomplex of TFIID, together with TAF1 and TAF2. Part of a TFIID complex containing TAF10 (TFIID alpha) and a TFIID complex lacking TAF10 (TFIID beta).
Synonyms: TAFII55; TAF2F
Tractability: Small molecule: a structure with a bound ligand is known. PROTAC: UniProt records ubiquitination sites on it; ubiquitination databases record sites on it; its protein half-life has been measured.
Gene: Protein-coding gene on chromosome 5 (141,259,884 to 141,320,784, reverse strand). Ensembl gene ENSG00000178913.
Subcellular location: Nucleus
Subcellular location (Human Protein Atlas): Nucleoplasm; Golgi apparatus
Pathways (Reactome):
Gene expression (Transcription): RNA Polymerase II Pre-transcription Events; RNA Polymerase II Promoter Escape; RNA Polymerase II Transcription Initiation; RNA Polymerase II Transcription Initiation And Promoter Clearance; RNA Polymerase II Transcription Pre-Initiation And Promoter Opening
Disease: HIV Transcription Initiation; RNA Polymerase II HIV Promoter Escape; Transcription of the HIV genome
Gene Ontology:
Molecular function: DNA-binding transcription factor binding; histone acetyltransferase binding; histone H3K27me3 reader activity; nuclear thyroid hormone receptor binding; nuclear vitamin D receptor binding; P-TEFb complex binding; protein binding; protein heterodimerization activity; RNA polymerase II general transcription initiation factor activity; TFIIH-class transcription factor complex binding; transcription cis-regulatory region binding
Biological process: DNA-templated transcription initiation; mRNA transcription by RNA polymerase II; negative regulation of DNA-templated transcription; negative regulation of MHC class I biosynthetic process; negative regulation of MHC class II biosynthetic process; negative regulation of protein kinase activity; negative regulation of transcription by RNA polymerase II; positive regulation of transcription by RNA polymerase II; positive regulation of transcription initiation by RNA polymerase II; regulation of transcription by RNA polymerase II; RNA polymerase II preinitiation complex assembly; transcription by RNA polymerase II; transcription initiation at RNA polymerase II promoter; positive regulation of DNA-templated transcription; regulation of DNA repair; spermine transport; chromatin organization
Cellular component: MLL1 complex; nucleus; transcription factor TFIID complex; transcription factor TFTC complex; transcription regulator complex; nucleoplasm; cytoplasm
Genetic constraint (gnomAD): Loss-of-function variants: 9 observed, 26.72 expected, observed/expected ratio (o/e) 0.34, 90% interval 0.2 to 0.59. The upper end of that interval is the gene's LOEUF score, 0.59, which puts it in group 2 of 6, group 1 being the genes least tolerant of losing a copy. Missense variants: 311 observed, 434.89 expected, observed/expected ratio (o/e) 0.72, 90% interval 0.65 to 0.79. Synonymous variants: 127 observed, 156.18 expected, observed/expected ratio (o/e) 0.81, 90% interval 0.7 to 0.94.
Homologues: Orthologues: macaque TAF7 (100% identical), dog TAF7 (99% identical), guinea pig TAF7 (99% identical), pig TAF7 (99% identical), rabbit TAF7 (98% identical), rat Slc25a2 (94% identical), mouse Taf7 (93% identical), tropical clawed frog taf7 (73% identical), zebrafish taf7 (73% identical), Drosophila melanogaster Taf7 (38% identical), Caenorhabditis elegans taf-7.2 (24% identical), Caenorhabditis elegans taf-7.1 (23% identical). Paralogues in human: TAF7L (60% identical).
Diseases named in the same sentence as TAF7 in open-access papers:
TAF7 is named in the same sentence as 24 diseases in open-access papers, as found by Europe PMC text mining. Sharing a sentence is not in itself a finding about the gene and the disease. The quoted sentences say what the papers report.
breast carcinoma (4 papers, 2019 to 2024). "MiR-374-5p has been shown to repress development of breast cancer through TATA-box binding protein associated factor 7 (TAF7)-mediated transcriptional regulation of DEP domain containing 1 (DEPDC1)." (PMID 35013577, 2022). "In conclusion, miR‐374c‐5p suppressed the development of breast cancer via targeting TAF7 to mediate DEPDC1, suggesting the part of miR‐374c‐5p as a latent therapeutic target for breast cancer patients." (PMID 31162714, 2019). "Here, we drew a conclusion that miR‐374c‐5p inhibited breast cancer development via TAF7‐mediated transcriptional regulation of DEPDC1." (PMID 31162714, 2019). "TAF7 may play an important role in cancer, as evidenced by a study of breast cancer that found significantly increased expression levels of TAF7 in tumor tissue, which was correlated with the invasive and metastatic potential of breast cancer." (PMID 38277205, 2024). "In addition, some studies noted that TAF7 was frequently overexpressed in various cancers through bioinformatics analysis and experimental verification including breast cancer 24, glioblastoma 25, lung adenocarcinoma 37 and colorectal cancer." (PMID 38904013, 2024). "Finally, rescue assays represented that miR‐374c‐5p suppressed breast cancer development via TAF7‐mediated transcriptional regulation of DEPDC1." (PMID 31162714, 2019). "We uncovered that overexpressed miR‐374c‐5p inhibited the development of breast cancer via TAF7‐regulated transcriptional regulation of DEPDC1, which may be a novel and vital proportion of cancer diagnosis and treatment strategies." (PMID 31162714, 2019). "miR‐374c‐5p modulating TAF7‐regulated DEPDC1 indeed influenced the carcinogenesis and progression of breast cancer." (PMID 31162714, 2019).
clear cell renal cell carcinoma (2 papers, 2024 to 2025). "Indeed, silencing TAF7 in clear cell renal cell carcinoma (ccRCC) cells inhibits their proliferation, reduces migration, and promotes apoptosis, further supporting the role of TAF7 in cell survival mechanisms." (PMID 39457533, 2024). "Additionally, silencing TAF7 in clear cell renal cell carcinoma (ccRCC) cells inhibits their proliferation, reduces migration, and promotes apoptosis, further supporting the role of TAF7 in cell survival mechanisms." (PMID 39457533, 2024). "In clear cell renal cell carcinoma, SETD7 catalyzes the methylation of lysine 5 and 300 on the TAF7 protein, leading to TAF7 deubiquitination and stabilization." (PMID 41203594, 2025).
lung adenocarcinoma (2 papers, 2024). A carcinoma that arises from the lung and is characterized by the presence of malignant glandular epithelial cells. "Additionally, other studies have found abnormal expression of TAF7 in various types of cancer, including gliomas and lung adenocarcinomas." (PMID 38277205, 2024).
breast invasive carcinoma (1 paper, 2024). "We found that the gene expression of TAF7 and TNF is induced upon tumorigenesis and more greatly overexpressed in response to the metastatic level of breast invasive carcinoma." (PMID 39457533, 2024). "In addition, we performed a differential gene expression analysis of TAF7 and TNF using RNA-Seq-based data from testicular germ cell tumors and breast invasive carcinoma." (PMID 39457533, 2024).
chronic kidney disease (1 paper, 2023). Impairment of the renal function secondary to chronic kidney damage persisting for three or more months. "Taken together, DNA-PKcs can be inhibited to correct metabolic reprogramming via the TAF7/mTORC1 signaling in chronic kidney disease, and serve as a potential target for treating chronic kidney disease." (PMID 36906617, 2023). "Here the authors report that the DNA-dependent protein kinase catalytic subunit (DNA-PKcs) drives chronic kidney disease progression in a study with male mice, potentially via TAF7/RAPTOR/mTORC1 signaling." (PMID 36906617, 2023).
Down syndrome (1 paper, 2016). "One is ERCC3 (aliase XPB), a gene with increased expression in Down syndrome which codes for an essential core subunit of the eukaryotic basal transcription factor complex TFIIH: defective TFIIH results, via TAF7, in thymocyte failure to reach DN4 stage." (PMID 26848775, 2016).
male infertility (1 paper, 2023). The inability of the male to effect fertilization of an ovum after a specified period of unprotected intercourse. "It has also been proved that taf7l, as a paralogue of taf7 (transcription initiation factor TFIID subunit 7), cooperates with trf2 to regulate spermiogenesis, and the variation of taf7 affects the genetic etiology of idiopathic male infertility." (PMID 37645057, 2023).
renal fibrosis (1 paper, 2023). A final common manifestation of a wide variety of chronic kidney diseases characterized by glomerulosclerosis and tubulointerstitial fibrosis. "Since DNA-PKcs is involved in the phosphorylation of TAF7 in renal fibrosis, we examined whether TAF7 deficiency may affect the dedifferentiation of renal epithelial cells or the activation and proliferation of interstitial fibroblasts induced by TGFβ1." (PMID 36906617, 2023). "Through subcellular localization analysis and knockdown of these proteins, we found that DNA-PKcs mediates renal fibrosis, perhaps through phosphorylation of TAF7, which is a subunit of TFIID." (PMID 36906617, 2023). "Our results indicate that TAF7 is a substrate for DNA-PKcs kinase activity and that DNA-PKcs-mediated phosphorylation of TAF7 aggravates renal fibrosis." (PMID 36906617, 2023). "Taken together, these data indicated that DNA-PK mediated phosphorylation of TAF7 aggravates renal fibrosis." (PMID 36906617, 2023).
testicular germ cell tumor (1 paper, 2024). A germ cell tumor arising from the testis. "We next analyzed the tumorigenic function of TAF7 and revealed that it is highly overexpressed in several types of human cancers, particularly testicular germ cell tumors, and associated with poor patient survival." (PMID 39457533, 2024). "Lastly, an analysis of patient survival with testicular germ cell tumors along with other types of cancers revealed high expression levels of both TAF7 and TNF, which were strongly associated with poor survival outcomes in patients." (PMID 39457533, 2024). "Indeed, a low and high expression of TAF7 and TNF in testicular germ cell tumors together could drive poor survival outcomes in patients, while a low and high expression of TAF7 or TNF in tumors alone is associated with extended longevity." (PMID 39457533, 2024). "Interestingly, testicular germ cell tumor patients co-expressing TNF and TAF7 had poorer survival outcomes compared to those with expression of TNF alone." (PMID 39457533, 2024).
tumor (7 papers, 2009 to 2025). "At the 31th day after injection, the tumor formed of shSETD7+TAF7-K5R group or shSETD7+TAF7-K300R group were significantly smaller than shSETD7+TAF7-WT group." (PMID 38904013, 2024). "Two non-PCDH genes are situated within the methylated domain; SLC25A2 was constitutively methylated in both normal tissues and tumours and TAF7 was constitutively unmethylated." (PMID 19956686, 2009). "We further checked their association with the regulation of tumor cell survival and cancer progression, finding that TAF7 is highly expressed in several cancers in comparison to normal tissues." (PMID 39457533, 2024). "Furthermore, CCNA2 presented a significant high expression trend in ccRCC tumor than in normal tissues and Pearson's r showed that TAF7 expression was positively correlated with CCNA2 expression." (PMID 38904013, 2024). "The abnormal expression of TAF7 is closely related to tumor development." (PMID 38904013, 2024). "In addition, we co-transfected 786-O and CAKI-1 cells with SETD7 siRNAs and TAF7 overexpressing plasmids to assess their potential counteracting effects on tumor cell proliferation and migration." (PMID 38904013, 2024). "The enrichment of transcription factors MYC and TAF7 in cluster 0, along with pathway enrichment analysis, revealed the activation of the MAPK pathway in these FABP6+ tumor cells." (PMID 38277205, 2024). "We found that XBP1, TAF7, ELF3, MYC, MAX, etc., were more enriched in tumor cells of luminal BC than the other two subtypes." (PMID 36077333, 2022). "TFs, such as XBP1, TAF7, ELF3, MYC, MAX, etc., were more enriched in tumor cells of luminal BC than the other two subtypes." (PMID 36077333, 2022).
cancer (5 papers, 2019 to 2024). A tumor composed of atypical neoplastic, often pleomorphic cells that invade other tissues. "Our anti-TAF2 antibody was able to immunoprecipitate endogenous TAF2, as well as core subunits of the TFIID complex, including TBP, TAF4, TAF5, TAF6, and TAF7, in nuclear extracts from colorectal HCT116, embryonic kidney HEK-293, and ovarian A2780 cancer lines." (PMID 38773077, 2024).
infection (3 papers, 2011 to 2025). The state of being infected such as from the introduction of a foreign agent such as serum, vaccine, antigenic substance or organism. "Additionally, the virus appears to modulate transcription factors STAT3/STAT5, NELFE, ATF2, TAF7, and others, enhancing cellular response to infection." (PMID 40725231, 2025). "In addition, the upregulation of the gene for the fundamental regulator of RNA polymerase II, TAF7, demonstrates that viral interference with the cell cycle and transcriptional regulation programs may be critical components during the establishment of a pathogenic infection in vivo." (PMID 22043290, 2011). "Depletion of TNFAIP3, ATF3, TAF7, and TRMT10C mildly to moderately reduced VEEV-TrD infection." (PMID 33788849, 2021). "TAF7 was recently demonstrated to also regulate the acetyl transferase activity of CIITA, which is the key factor in TAF1-independent transcription of MHC class I and II in response to infection." (PMID 22043290, 2011). "One could therefore speculate whether TAF7 is utilized, by the virus, in the control of MHC antigen presentation during infection; and does this also extend to the control of the cell cycle program?" (PMID 22043290, 2011).
TAF7 also shares sentences with these, for which no sentence is quoted: prostate carcinoma (2 papers); asthma (1); bladder carcinoma (1); colorectal cancer (1); esophageal tumors (1); glioblastoma (1); glioma (1); hepatocellular carcinoma (1); lung carcinoma (1); nasopharyngeal carcinoma (1); retinoblastoma (1); testis cancers (1).